LRRK2 (leucine rich repeat kinase 2)
Diseases named in the same sentence as LRRK2 in open-access papers (continued):
Sharing a sentence is not in itself a finding about the gene and the disease.
Parkinson disease (continued). "Of the 123 patients with Parkinson disease–associated genetic mutations, 115 (93.5%; 46 LRRK2, 33 GBA, 18 homozygous PRKN, and 18 heterozygous PRKN) were included in the meta-analysis for motor end points, and 8 single cases (6.5%) underwent intraindividual patient analyses." (PMID 30707228, 2019). "Mutations that activate LRRK2 protein kinase cause Parkinson’s disease." (PMID 31663853, 2019). "Treatment with STN DBS for patients with Parkinson disease with LRRK2, GBA, or PRKN mutations appears to be associated with similar motor outcomes but different changes in dopaminergic dose, activities of daily living, motor complications, and cognitive functions." (PMID 30707228, 2019). "Interestingly, the Lrrk2 gene, mutations in which contribute to Parkinson’s disease, is positively correlated with neurite branchiness (number of branch points per μm) in the class-conditional model, but not the class-independent model (q = 0.049)." (PMID 31211786, 2019). "Among the 123 patients with Parkinson disease–associated genetic mutations, 80 (65.0%) (27 LRRK2, 30 GBA, 12 homozygous PRKN, and 11 heterozygous PRKN) were included in the meta-analysis for therapy end points, and 7 single cases (5.7%) underwent intraindividual patient analyses." (PMID 30707228, 2019). "Here we use multiple models and techniques to identify the pathways through which LRRK2 mutations may lead to the development of Parkinson's disease." (PMID 30954703, 2019). "This case report suggests that cocaine abuse indeed might be linked to secondary Parkinsonism and serves as an example of a potential gene-environmental interaction between the detected LRRK2 risk variant and cocaine abuse." (PMID 31660902, 2019). "Interestingly, we find comparable molecular dys-regulations in fibroblasts from Parkinson’s patients with G2019S mutated LRRK2." (PMID 30872638, 2019). "Furthermore, LRRK2-mediated Rab10 phosphorylation is increased in neutrophils as well as monocytes isolated from three Parkinson's patients with a heterozygous VPS35[D620N] mutation compared with healthy donors and idiopathic Parkinson's patients." (PMID 29743203, 2018). "Mutations in LRRK2 are observed in ∼1% of sporadic and ∼5% of familial Parkinson's patients." (PMID 29127256, 2018). "To further demonstrate the utility of this method to study CNS disease pathogenesis, we employed this differentiation procedure to generate A-3D cultures using PPMI-51625, a hiPSC line derived from a Parkinson’s disease patient carrying the G2019S mutation in the LRRK2 gene." (PMID 29751846, 2018). "Furthermore, a recent report indicated that Sec16A interacts with the GTPase domain of LRRK2, a protein produced by the causative gene for Parkinson’s disease, and observed that LRRK2 regulates the function of Sec16A." (PMID 29300766, 2018). "Mutations in LRRK2 cause familial autosomal-dominant forms of Parkinson’s disease (PD)." (PMID 30483055, 2018). "We examined brains of tau transgenic flies homozygous for the Lrrk mutant allele or expressing either wild-type Lrrk or Lrrk carrying the G1914S mutation (Lrrk-GS), the mutation homologous to the most common Parkinson disease—associated mutation in human LRRK2 (G2019S)." (PMID 30571694, 2018). "Mutations that activate the LRRK2 (leucine-rich repeat protein kinase 2) protein kinase predispose to Parkinson's disease, suggesting that LRRK2 inhibitors might have therapeutic benefit." (PMID 29127256, 2018). "We speculate that G2019S LRRK2 mutation carriers would have the highest levels of Rab10 phosphorylation followed by those with sporadic Parkinson's, while healthy controls would have the lowest levels." (PMID 29127255, 2018).
Parkinson disease (continued). "Furthermore, we elaborate methods to quantitatively assess LRRK2-mediated Rab10 phosphorylation in human neutrophils including the study of a few clinical samples from LRRK2 G2019S associated and sporadic Parkinson's patients as well as controls." (PMID 29127255, 2018). "Drosophila models for leucine-rich repeat kinase 2 (LRRK2)-associated Parkinson’s disease." (PMID 29686647, 2018). "It would also be interesting to investigate whether Parkinson's patients with PARK16 mutations display elevated LRRK2 kinase activity and Rab10 phosphorylation." (PMID 29212815, 2018). "Collectively, 14-3-3 proteins play an important role in LRRK2 mutant-linked Parkinsonism." (PMID 30464741, 2018). "Mutations in LRRK2 kinase are associated with Parkinson’s disease." (PMID 30150626, 2018). "Interestingly, expression of wild-type fly Lrrk also enhanced tau neurotoxicity, with a further enhancement in neurotoxicity when Lrrk harboring mutations homologous to Parkinson disease—associated mutations in human LRRK2 were expressed." (PMID 30571694, 2018). "Additionally, studies have shown how the most common genetic cause of Parkinson's disease, G2019S mutations in the leucine-rich repeat kinase 2 gene (LRRK2), displayed uncoupling and low RCR implicating UCP2 and -4 proteins." (PMID 28360103, 2017). "This screen included 507 healthy controls and patients with genetic neurological diseases that have a higher prevalence in the Basque population, including 20 patients with myotonic dystrophy type 1 and 57 with Parkinson’s disease related to the LRRK2 mutation." (PMID 28594853, 2017). "First, the relevance of autophagy in Parkinson's disease will be evaluated giving a brief overview of all the relevant Parkinson's disease genes; then, the association of LRRK2 with macroautophagy and the endolysosomal pathway will be analyzed based on the supporting literature." (PMID 28202669, 2017). "Since some pathogenic LRRK2 mutations enhance this effect while the protective R1398H variant relieves it, our data strengthen the notion that decreased canonical Wnt activity is central to Parkinson’s disease pathogenesis." (PMID 28103901, 2017). "The LRRK2 mutation is a major causal mutation in familial Parkinson's disease." (PMID 27314038, 2016). "Understanding how LRRK2 mutations impact upon the function of dopaminergic neurons is important for elucidating the key pathophysiological changes underlying the core symptoms of Parkinson's disease." (PMID 26744332, 2016). "In addition, as genetic etiology of Parkinson's disease, it has been well known that induced neural stem cells (iNSCs) were progressively depleted by LRRK2 gene mutation, LRRK2 (G2019S)." (PMID 28074097, 2016). "Overall, our findings support a novel physiological role for LRRK2 in regulating CaV2.1 function that could have implications for how mutations in LRRK2 contribute to Parkinson’s disease pathophysiology." (PMID 27242426, 2016). "Leucine rich repeat kinase 2 is one of the key genetic factors contributing to the risk of developing Parkinson’s disease (PD), an irreversible, progressive neurodegenerative movement disorder primarily associated with neuronal cell loss in the Substantia nigra pars compacta." (PMID 27731364, 2016). "In Parkinson's disease, mutations of LE/lysosome proteins and motor complexes, such as LRRK2, Vps35, DCTN1, have been previously documented, suggesting that LE sorting defect and axonal transport disruption could play a causal role in this pathology." (PMID 26685126, 2016). "We also assayed the sensitivity of ONS cells from patients with monogenic forms of Parkinson’s disease, LRRK2 and PINK-1 mutations, in particular (percentage change at 24 hours = -0.71%, 48 hours = -6.94%, 72 hours = -7.84% 96 hours = -11.67% and 120 hours = -11.89%)." (PMID 27123847, 2016). "A common genetic form of Parkinson's disease (PD) is caused by mutations in LRRK2." (PMID 27273569, 2016).
Parkinson disease (continued). "In addition, treatment with HDAC6 inhibitors, which increase acetylation of α-tubulin, reverses transport defects in cellular models of Huntington's disease and LRRK2 mutation-induced Parkinson's disease." (PMID 28105056, 2016). "And we also propose adoption of an ideal gene therapy approach that combines the gene-correction process with the TD process, focusing on the example of the pathogenic LRRK2 mutant (G2019S), which progressively depletes neural stem cells in Parkinson's disease." (PMID 28074097, 2016). "Parkinson's disease gene leucine-rich repeat kinase 2 (LRRK2) has been implicated in a number of processes including the regulation of mitochondrial function, autophagy and endocytic dynamics; nevertheless, we know little about its potential role in the regulation of synaptic plasticity." (PMID 27432119, 2016). "Given that the most common Parkinson’s disease LRRK2 G2019S mutation displays increased kinase activity, our results suggest that mutant LRRK2 may impair synaptic vesicle dynamics via aberrant phosphorylation of NSF." (PMID 26758690, 2016). "In a mouse model, the Parkinson disease (PD)-associated mutation in LRRK2 affects excitatory postsynaptic signaling in the hippocampus and LRRK2 kinase activity increases as mice age, suggesting that developmental alterations of excitatory synaptic activity relate to long-term outcomes." (PMID 29051423, 2016). "LRRK2-Parkinson Disease patients with associated REM sleep behavior disorder." (PMID 26177462, 2015). "Interestingly, the deletion of this domain in the Zebrafish LRRK2 ortholog (zLRRK2) causes parkinsonism-like phenotype including loss of dopaminergic neurons in diencephalon and locomotion defects." (PMID 25980689, 2015). "Lrrk2, which encodes leucine-rich repeat kinase 2, may play a role in monocyte maturation and variants of this gene is associated with an increased risk of both Parkinson’s and Crohn’s disease." (PMID 25674539, 2015). "The effect is enhanced by a Parkinson’s-disease associated mutation of LRRK2." (PMID 26355680, 2015). "Additional studies are needed to further investigate the impact of Lrrk2 deficiency on the immune response, particularly in view of the LRRK2 gene’s involvement in the pathogenesis of Parkinson’s disease, a condition in which inflammation plays an important role." (PMID 26067490, 2015). "We have curated interactions involving LRRK2, a protein of largely unknown function linked to familial forms of Parkinson's disease, and hosted the data in the IntAct database." (PMID 25648416, 2015). "The most common mutation of LRRK2 found in Parkinson’s disease is G2019S in the kinase domain." (PMID 24926233, 2014). "Mutations in the gene encoding leucine-rich repeat kinase 2 (LRRK2) are a common genetic cause of Parkinson disease, but the mechanisms whereby LRRK2 is regulated are unknown." (PMID 24942733, 2014). "How the ROC domain contributes to these disease phenotypes is not clear, although the location of mutations (for example, the R1441C mutation) in the ROC domain causative for Parkinson’s disease has focused a great deal of research on this aspect of LRRK2 biology." (PMID 24981771, 2014). "Mutations in the kinase LRRK2 are associated with Parkinson’s disease." (PMID 25316291, 2014). "Taken together, our data shed light on the nature of the LRRK2-tubulin interaction, and indicate that alterations in microtubule stability caused by changes in LRRK2 might contribute to the pathogenesis of Parkinson disease." (PMID 24275654, 2014). "In addition, in other familial forms of parkinsonism linked to PARKIN or LRRK2 gene mutations, the inconsistent accumulation of tau, αsyn, neither, or both proteins has been observed." (PMID 25352339, 2014).
Parkinson disease (continued). "The central role of this protein in Parkinson's disease (PD) has been highlighted by the discovery of autosomal dominant mutations in LRRK2 causing familial Parkinson's disease and the subsequent identification of the LRRK2 locus as a risk factor for sporadic disease." (PMID 23916833, 2013). "The strong genetic association identified between LRRK2 mutations and Parkinson’s disease has captured the attention of the research community, with much interest focusing on whether LRRK2 modulation will be a viable strategy for treating the disease." (PMID 23799078, 2013). "The asymmetry of radioligand uptake in Parkinsons disease associated with GBA or LRRK2 mutations suggests that interactions with additional genetic or environmental factors may be associated with dopaminergic neuronal loss." (PMID 23935950, 2013). "Both LRRK2 and Parkinson’s disease pathogenesis have been linked to macroautophagy." (PMID 23754980, 2013). "Mutations in the LRRK2 gene are the most common cause of Parkinson's disease identified to date, but the pathogenic mechanism remains unclear." (PMID 24133413, 2013). "In 2004 it was first shown that mutations in LRRK2 can cause Parkinson's disease." (PMID 23938341, 2013). "These include those with LRRK2 mutations, who represent approximately 0.5–1.0% of unselected Parkinson disease cases in the general western communities, although considerably greater proportions of familial Parkinson disease or those of Ashkenazi Jewish origin." (PMID 23823465, 2013). "These include LRRK2, a gene that encodes a kinase involved in Parkinsons Disease." (PMID 24070420, 2013). "An elegant demonstration of the superiority of an isogenic cell line study design over a study design comparing iPSC lines from patients versus control individuals was provided by a recent study of a mutation in the LRRK2 gene, which is implicated in Parkinson disease." (PMID 23751357, 2013). "For example, increased FoxO3a has been found localized to Lewy bodies and Lewy neurites in Parkinson’s disease brain tissue and activation of FoxO by LRRK2, associated with autosomal-dominant late-onset Parkinson’s disease, enhances neuronal cell death in Drosophila." (PMID 22804756, 2012). "Mutations in the leucine-rich repeat kinase-2 (LRRK2) have been linked to Parkinson’s disease." (PMID 22952710, 2012). "That LRRK2 is phosphorylated during inflammatory signalling is of interest as increasing evidence suggests that inflammation is linked to the progression of neurodegeneration and Parkinson’s disease." (PMID 22723946, 2012). "LRRK2 mutations may cause Parkinson's disease and cell death by impairing protein degradation pathways, leading to protein accumulation and aggregation over time." (PMID 22230652, 2012). "This binding may be linked to Parkinson’s disease as phosphorylation of Ser910 and Ser935 and 14-3-3 binding is inhibited by five of the six validated LRRK2 pathogenic mutations (R1441C, R1441G, R1441H, Y1699C and I2020T)." (PMID 22723946, 2012). "Dominantly inherited missense mutations in leucine-rich repeat kinase 2 (LRRK2) are the most common genetic cause of Parkinson's disease, but its normal physiological function remains unclear." (PMID 22230652, 2012). "Mutations in LRRK2 are strongly linked to Parkinson’s disease (PD)." (PMID 23190742, 2012). "It will also be exciting to determine whether defects in LRRK2 signalling in immune cells are linked to the development of Parkinson’s disease in patients with LRRK2 mutations." (PMID 22723946, 2012). "Mutations in the LRRK2 gene are the most common cause of genetic Parkinson’s disease." (PMID 22647713, 2012). "Different ethnic groups may share the same risk loci such as SNCA and LRRK2 for Parkinson's disease (PD) in Japanese and European cohorts while other loci may show population specificity (e.g. MAPT in PD)." (PMID 21390209, 2011).
Parkinson disease (continued). "In summary, the effective shRNA against LRRK2 R1441 alleles described herein suggests that RNAi-based therapy of inherited Parkinson's disease is a viable approach towards developing effective therapeutic interventions for this serious neurodegenerative disease." (PMID 21712955, 2011). "What may be the pathophysiological relevance of our findings in differentiating neurons to human Parkinson's disease patients carrying LRRK2 mutations?" (PMID 21695257, 2011). "Mutation of leucine-rich repeat kinase 2 (LRRK2) is the leading genetic cause of Parkinson's Disease (PD), manifested as age-dependent dopaminergic neurodegeneration, but the underlying molecular mechanisms remain unclear." (PMID 21857923, 2011). "Frequency of LRRK2 mutations in early-and late-onset Parkinson disease." (PMID 21034472, 2010). "The multidomain protein kinase LRRK2 is an attractive therapeutic target as it was shown that this previously unknown kinase can cause Parkinson's disease (PD) if mutated." (PMID 21048939, 2010). "Nevertheless, further studies will be required to ascertain whether the association between LRRK2 parkinsonism and cancer is real or coincidental." (PMID 21203498, 2010). "Previous findings reported an interesting and unexpected interaction of LRRK2 with parkin, suggesting that a direct interaction between these two genetic causes of parkinsonism may be involved in a common pathogenic pathway." (PMID 20976090, 2010). "Moreover, of the 18 known mutation carriers of a large family with LRRK2 R1441C parkinsonism, four had colon cancer." (PMID 21203498, 2010). "Although agreat deal of further analysis is required to work out how 14-3-3 binding regulates LRRK2, theseresults suggest that disrupting the interaction of LRRK2 with 14-3-3 could be linked to Parkinson'sdisease." (PMID 20659021, 2010). "In 2004, mutations in the LRRK2 gene were first described and turned out to be the most frequent genetic cause of familial and sporadic Parkinson's disease and may account for up to 40% of patients in distinct populations." (PMID 18986509, 2008). "The co-localization of the protein kinase LRRK2 in LBs may provide a molecular mechanism underlying divergent causes associated with parkinsonism, including aberrant protein phosphorylation and subsequent protein aggregation mediated by α-synuclein and parkin." (PMID 17137507, 2006). "While several studies have identified dysregulated miRNAs in sporadic Parkinson’s disease, it remains unclear whether distinguishable alterations of cell-free miRNAs occur in genetic forms of the disease, such as those associated with the LRRK2 G2019S mutation." (PMID 41298996, 2025). "Thus, our study is the first to evaluate the effects of homotaurine on osteogenic differentiation, highlighting its potential implications for patients with Parkinson’s disease, particularly those with LRRK2 mutations, who often experience compromised bone homeostasis." (PMID 40227236, 2025). "Altogether, these experiments highlight the pathogenic LRRK2-triggered loss of neuroprotection experienced by multiple neuron classes, because of a block in Shh signaling and neuroprotective factor production that has important implications for dopaminergic neuron survival in Parkinson’s disease." (PMID 39537338, 2025). "Leucine-rich repeat kinase 2 (LRRK2) mutations are the most common genetic cause of Parkinson disease (PD)." (PMID 38652325, 2024). "Parkinson’s disease is a complex disease mainly characterized by movement disorder associated with a selective degeneration of DAergic neurons believed to deteriorate by the interaction of genes (e.g., LRRK2) and environmental factors (e.g., exposure to neurotoxin PQ)." (PMID 38847910, 2024).